FGFR2 (fibroblast growth factor receptor 2)
Diseases named in the same sentence as FGFR2 in open-access papers (continued):
Sharing a sentence is not in itself a finding about the gene and the disease.
squamous cell carcinoma (9 papers, 2009 to 2024). A carcinoma arising from squamous epithelial cells. "FGFR2 fusions were detected in one case each of adenocarcinoma and squamous cell carcinoma." (PMID 39507756, 2024). "FGFR2, FGFR3, and FGFR4 expression were elevated in squamous cell carcinoma, and a high expression of FGFR1, FGFR2, FGFR3, and FGFR4 were associated with a less aggressive phenotype." (PMID 27154171, 2016). "FGFR1 was more highly expressed in adeno-/adenosquamous carcinoma, while FGFR2, FGFR3, and FGFR4 expression was more prominent in squamous cell carcinoma (P = 0.020, P < 0.001, P < 0.001, and P = 0.020, respectively)." (PMID 27154171, 2016). "FGFR1 was highly expressed in adeno-/adenosquamous carcinoma (P = 0.020), while FGFR2, FGFR3, and FGFR4 expression were more prominent in squamous cell carcinoma (P < 0.001, P < 0.001, and P = 0.020, respectively)." (PMID 27154171, 2016). "Moreover, in Squamous Cell Carcinoma (SCC), where ΔNp63α drives proliferation and blocks apoptosis, it has recently been shown that the Fibroblast Growth Factor Receptor 2 (FGFR2) is the crucial mediator of ΔNp63 oncogenic functions." (PMID 31781486, 2019). "While FGFR1 amplifications have been found in up to 22% of squamous cell carcinomas of the lung and about 15% in head and neck cancers, we found neither FGFR1, FGFR2, nor FGFR3 amplifications by FISH in squamous differentiated bladder cancer." (PMID 27669755, 2016).
esophageal adenocarcinoma (8 papers, 2014 to 2025). A malignant tumor with glandular differentiation arising predominantly from Barrett mucosa in the lower third of the esophagus. "The sex and age distribution in FGFR2 amplified tumors was comparable to the overall esophageal adenocarcinoma cohort." (PMID 36416959, 2023). "Primary operated patients with FGFR2-amplified esophageal adenocarcinoma showed a tendency to a worse prognosis (overall survival)." (PMID 36416959, 2023). "From 144 cases with primary esophageal adenocarcinoma and corresponding lymph node metastases, 10 tumor pairs showed FGFR2 amplification." (PMID 36416959, 2023). "(c) What is the actual relevance of FGFR2 amplification in adenocarcinoma of the esophagus?" (PMID 36416959, 2023). "We previously identified FGFR2 amplification in esophageal adenocarcinoma." (PMID 26933914, 2016). "The proportion of FGFR2-amplified adenocarcinomas was higher in treatment-naïve patients (13/144, 7.3%) than in neoadjuvant-treated patients (8/252, 3.2%), resulting in an approximate 1/3 to 2/3 distribution of naïve to neoadjuvant-treated tumors within FGFR2-amplified esophageal adenocarcinomas." (PMID 36416959, 2023). "FGFR2-amplified esophageal adenocarcinomas (4.9%) showed no specific clinical or histomorphological characteristics." (PMID 36416959, 2023). "Amplification of FGFR2 has been reported to occur in 5–10% of gastric and esophageal adenocarcinomas by SNP array analysis, but we did not see evidence of copy number gain in our cohort." (PMID 24454681, 2014).
esophageal squamous cell carcinoma (8 papers, 2013 to 2026). Esophageal squamous cell carcinoma (ESCC) is a type of esophageal carcinoma (EC) that can affect any part of the esophagus, but is usually located in the upper or middle third. "In Barrett's neoplasia, we found LGD and HGD to be more difficult to distinguish than esophageal SCC because BE has higher FGFR2 expression than normal squamous epithelium." (PMID 29152066, 2017). "In addition to Barrett's neoplasia, FGFR2 is overexpressed in other epithelial-derived cancers, including esophageal SCC, gastric, esophagogastric junction, colorectal, pancreatic, and breast." (PMID 29152066, 2017). "In our previous study, we found that FGFR2 (FGFR2 mentioned in our study is FGFR2-IIIc) was a specific surface marker of CAFs in esophageal squamous cell carcinoma (ESCC)." (PMID 35941662, 2022). "Using FGFR2 as a tracing marker, we identified a novel origin of CAFs in esophageal squamous cell carcinoma (ESCC)." (PMID 35941662, 2022).
liver fibrosis (8 papers, 2018 to 2026). "FGFR2 (fibroblast growth factor receptor 2), which was found to be hypomethylated across these studies, has been linked with liver fibrosis." (PMID 30005700, 2018). "Cynaroside blocked the activation and development of liver fibrosis by inhibiting the overexpression of FGFR2 and the excess of basic fibroblast growth factor (bFGF), thus reducing hepatic stellate cell (HSC) activation and collagen secretion in hepatocytes." (PMID 40822468, 2025). "Based on our data mining of the transcriptome sequences of human and murine liver fibrosis, we discovered a correlation between FGFR2 overexpression and liver fibrosis." (PMID 37111305, 2023). "Targeting overactivated Fibroblast growth factor receptor 2 (FGFR2) is a promising strategy to counteract collagen accumulation during liver fibrosis." (PMID 37111305, 2023). "With the aim of discovering a therapeutic agent to inhibit FGFR2 and mitigate liver fibrosis, high-throughput affinity screening based on surface plasmon resonance (SPR) sensor chips were carried out with a natural compound library." (PMID 37111305, 2023). "In this study, the correlation between FGFR2 expression and liver fibrosis development was demonstrated through data mining." (PMID 37111305, 2023). "In past studies, FGFR2 has shown the potential to be used as a target for the treatment of liver fibrosis." (PMID 37111305, 2023). "The expression of FGFR2 was found to be elevated in liver fibrosis patients with backgrounds of Hepatitis B infection (2.30-fold), alcohol abuse (1.60-fold), and non-alcoholic steatohepatitis (NASH, 2.03-fold) through a comparison with normal individuals." (PMID 37111305, 2023). "Data mining, cell validation, and animal studies showed a positive correlation between FGFR2 overexpression and liver fibrosis development." (PMID 37111305, 2023). "In conclusion, this study has shown that high expression of FGFR2 is correlated with liver fibrosis and that FGFR2 drives the process of liver fibrosis." (PMID 37111305, 2023). "Other DNA methylation studies have also found a number of common differentially methylated sites, including the fibroblast growth factor receptor 2 (FGFR2) involved in liver fibrosis." (PMID 33193730, 2020). "Furthermore, the analysis of FGFR2 expression during liver fibrosis regression revealed that the expression was decreased in patients whose fibrosis was in remission but unchanged in those who failed to be cured." (PMID 37111305, 2023). "Overall, these studies suggest that FGFR2 plays a crucial role in the development of liver fibrosis, and the targeting of FGFR2 using specific inhibitors may be a potential therapeutic strategy for treating liver fibrosis." (PMID 37111305, 2023). "In addition, the genetic knockdown of FGFR2 has been shown to reduce liver fibrosis in various animal models." (PMID 37111305, 2023). "Current evidence suggests that FGFR2 may be a promising target, but more research is needed to determine the efficacy of FGFR2 as a target for liver fibrosis treatment as well as to fully understand the mechanisms behind its involvement in TGF-β signaling." (PMID 37111305, 2023). "In order to verify the regulatory role of FGFR2 in the development of liver fibrosis, two cell lines were established, i.e., the FGFR2 overexpressing HSC cell line (LX-2) and the liver cell line (Huh-7), and the sensitivity changes induced by TGF-β were compared between the two cell lines." (PMID 37111305, 2023). "However, there is a shortage of drugs to specifically block the activation of FGFR2 in liver fibrosis patients." (PMID 37111305, 2023). "FGFR2 was also upregulated by 2.47-fold in the livers of mice with CCl4-induced liver fibrosis." (PMID 37111305, 2023).
liver fibrosis (continued). "The upregulation of FGFR2 in liver fibrosis patients was confirmed by various methods, including immunohistochemistry (IHC), Western blot quantification, and reverse transcription quantitative real-time PCR (RT-qPCR) quantification on liver tissue samples collected from clinical volunteers." (PMID 37111305, 2023). "Recent evidence suggests that sorafenib, an anticancer drug targeting FGFR2, may have the potential to treat liver fibrosis." (PMID 37111305, 2023). "Our discovery that IRS2 silencing in HSCs also promoted fibrogenesis while limiting hepatocyte differentiation and FGFR2-IIIb expression in coculture recapitulated the increase in liver fibrosis and reduced Fgf7/Fgfr2-IIIb expression described in Irs2−/− mice during DDC treatment." (PMID 30695023, 2019). "Fibroblast growth factor receptor 2 (FGFR2) is a tyrosine kinase receptor that activates MAPK and Wnt signaling and plays a crucial role in the development of liver fibrosis." (PMID 37111305, 2023). "The inhibitory effect of CYN on the fibrosis-promoting effect of FGFR2 was also demonstrated, as CYN reduced the sensitivity of cells to TGF-β induction and mitigated the development of liver fibrosis." (PMID 37111305, 2023). "It was observed that FGFR2 knockdown significantly reduced the expression of collagen I and TGF-β1, key markers of liver fibrosis." (PMID 37111305, 2023).
brain tumors (7 papers, 2015 to 2025). "We showed that CSF ctDNA is more representative of brain tumour genomic alterations than plasma and putative actionable gene mutations and CNA (that is, EGFR, PTEN, ESR1, IDH1, ERBB2, FGFR2) can be identified." (PMID 26554728, 2015). "Notably, important oncogenes involved in brain tumor development are located on these chromosomes, such as PDGFR1 and FGFR2 on chromosome 4, EGFR and MET on chromosome 7, and CDK4 and MDM2 on chromosome 12." (PMID 41323387, 2025). "The rates of alterations of the FGFR1, FGFR2, FGFR3, and FGFR4 genes in brain tumor patient samples were 1%, 1.5%, 1.7%, and 0.9%, respectively, and pediatric brain tumors had among the highest levels of FGFR gene family alterations among all brain tumor databases." (PMID 40510032, 2025). "During this procedure, SNUH utilized NGS with a brain tumour-targeted gene panel, identifying the TPM3::NTRK1 fusion, amplification of MDM4/AKT3, and one-copy loss of PTEN/FGFR2, leading to the diagnosis of the tumour as HGG, not otherwise specified (NOS), according to the WHO2021 criteria." (PMID 39014476, 2024).
cleft palate (7 papers, 2013 to 2024). Cleft palate is a fissure type embryopathy that affects the soft and hard palate to varying degrees. "The pathogenic variants in FGFR2 potentially alter a complex signaling network in epithelial–mesenchymal interactions during palatogenesis resulting in cleft palate." (PMID 35997397, 2022). "Mutations in Fgf16 or Fgfr2 are associated with cleft palate, and suppression of Fgfr signaling via Fgfr kinase inhibitors causes palate defects." (PMID 31596367, 2019). "The ChIP-seq data also identified p63-bound regions associated with Pvrl1, Irf6, Fgfr2, Tcfap2a, Pdgfa, Sfn, Grhl3 and Jag2, mutations in which result in cleft palate." (PMID 28604778, 2017). "Consistent with this work, we identified a large number of p63 binding sites that are known to regulate genes associated with cleft palate including Pvrl1, Fgfr2 and Pdgfa demonstrating for the first time that p63 transcriptionally regulates these genes in the palatal epithelia." (PMID 28604778, 2017).
hyperphosphatemia (7 papers, 2017 to 2025). Abnormally high level of phosphate in the blood. "The liquid CGP was useful for detecting FGFR2 fusion and the patient experienced typical side effects (nail disorders, hyperphosphatemia, and taste disorders) of pemigatinib that required treatment." (PMID 37415592, 2023). "The patient experienced low-grade hypercalcaemia and hyperphosphataemia: these derive from inhibition of FGFR1 (most compounds in late clinical development have pan-FGFR-inhibitory activity; FGFR2-selective agents are in early drug development)." (PMID 38895132, 2024). "In pre-clinical studies, lirafugratinib inhibited FGFR2 phosphorylation, downstream signalling and proliferation of FGFR2-amplified SNU-16 GC cells in vitro and in vivo, and notably induced significantly less hyperphosphatemia compared to pan-FGFR inhibitors." (PMID 38791079, 2024).
Jackson-Weiss syndrome (7 papers, 2009 to 2024). Jackson-Weiss syndrome (JWS) is a rare genetic disorder characterized by foot malformations (tarsal and metatarsal fusions; short, broad, medially deviated great toes) and in some patients craniosynostosis with facial anomalies. "Apert, Pfeiffer, Crouzon, and Jackson-Weiss syndromes are due to gain-of-function mutations of FGFR2 in either the Ig II-III linker region (Apert) or the Ig III domain." (PMID 19968867, 2009).
liver cancer (7 papers, 2015 to 2024). An epithelial or non-epithelial malignant neoplasm that arises from the liver. "In this study, we found that snoRD126 binds to hnRNPK and regulates FGFR2 expression, promoting the development of liver cancer." (PMID 33891563, 2021). "FGFR1S602F was reported in only one case of melanomaand FGFR2, and FGFR4 mutations were found in 4/231 (1.7%) and 1/231 (0.4%) liver cancer samples, respectively." (PMID 27384874, 2016). "Recent studies have shown the occurrence of recurrent FGFR2 fusion events in iCCA patients (16% of patients); FGFR2 fusions are very rare in other primary liver tumors, being virtually absent in HCCs." (PMID 28930164, 2017).
Obesity (7 papers, 2015 to 2022). Accumulation of substantial excess body fat. "ACP cystic fluid caused growth retardation and an increased obesity index in mice, affected the expression of the Npy, Fgfr2, Rnpc3, Sst, and Pcsk1n genes that regulate growth and energy metabolism in hypothalamic neurons, and enhanced the cellular interaction of Agrp–Mc3r." (PMID 35525962, 2022).
oligodendroglioma (7 papers, 2020 to 2024). A well-differentiated (WHO grade II), diffusely infiltrating neuroglial tumor, typically located in the cerebral hemispheres. "In fact, the diagnosis of PLNTY relies on the following essential criteria: “diffuse growth pattern and oligodendroglioma-like component and few (if any) mitotic figures and regional CD34 expression and IDH-wild type status and BRAF V600E mutation or FGFR2 or 3 fusions”." (PMID 36647073, 2023). "In our cohort of IDH-mutant diffuse glioma, EGFR Amp was found to co-occur with FGFR1, FGFR2, NTRK3 and RB1 alterations, which was not completely consistent in astrocytoma and oligodendroglioma." (PMID 38595969, 2024).
bent bone dysplasia (6 papers, 2021 to 2025). "On the other hand, loss-of-function missense FGFR2 variants in the trans-membrane (TM) domain have been found in Bent Bone Dysplasia." (PMID 40362441, 2025). "FGFR2 gain- and loss-of-function mutations have been associated with multiple skeletal syndromes such as bent bone dysplasia, in which long bones are bent and contain smaller hypertrophic chondrocytes in the growth plate and a thickened periosteum." (PMID 36994096, 2023).
bile duct cancer (6 papers, 2021 to 2025). "A long-term follow up of this subgroup of CC patients is needed to confirm if elevated expression of CEBPB and FGFR2 is associated with the higher incidence of bile duct cancer in these patients." (PMID 36996081, 2023). "In line with the presence of cholangiocyte-like cells in HB, and elevated expression of FGFR2 in bile duct cancer, percentages of FGFR2-immuno-positive bile duct cells were the highest in HB tumor region as compared to CC and HB non-tumor livers." (PMID 36996081, 2023). "Future study to address the efficacy of FGFR2 and CEBPB as neo-biomarkers for cancer risk stratification of CC patients and drug targets for bile duct cancer treatment in a larger patient cohort with long-term follow up is warranted." (PMID 36996081, 2023). "According to several completed trials, FDA approved agents targeting IDH1 and FGFR2 for bile duct cancers progressing after standard chemotherapy." (PMID 36199981, 2022).
LADD syndrome (6 papers, 2008 to 2024). "LADD syndrome is an autosomal dominant disorder caused due to mutations in one of at least three genes, the fibroblast growth factor receptor 2 (FGFR2), fibroblast growth factor receptor 3 (FGFR3), and fibroblast growth factor 10 (FGF10)." (PMID 27803819, 2016). "Similar defects might be present also in humans and explain a part of the phenotype LADD syndrome caused by mutations in FGF10 or FGFR2." (PMID 30505318, 2018). "Sequence alterations in the intracellular tyrosine-kinase domains of FGFR2 and FGFR3 were described to be involved in LADD syndrome, and aberrations of the FGF10 gene were found to be associated with both the ALSG and the LADD syndrome." (PMID 19102732, 2008).
neuroepithelial tumor (6 papers, 2020 to 2024). "FGFR2 or FGFR3 gene fusions are also a characteristic molecular feature of a recently described subtype of low grade neuroepithelial tumour—Polymorphous Low-grade Neuroepithelial Tumour of the Young (PLNTY)." (PMID 37130917, 2023). "Taking both morpho-molecular and methylation profiling data from this tumor, we refined the diagnosis to a polymorphous low-grade neuroepithelial tumor of the young (PLNTY) with FGFR2 fusion." (PMID 33803647, 2021). "A recently described entity, “polymorphous low-grade neuroepithelial tumor of the young” or “PLNTY”, has been shown to harbor molecular abnormalities involving the MAPK pathway, including FGFR genes, and a unique fusion involving FGFR2." (PMID 32085805, 2020).
Saethre-Chotzen syndrome (6 papers, 2014 to 2023). Saethre-Chotzen syndrome (SCS) is an inherited craniosynostosis syndrome characterized by unilateral or bilateral coronal synostosis, facial asymmetry, ptosis, strabismus and small ears with prominent crus, among other less common manifestations. "Mutations in FGFR2 have not been shown to cause lineage mixing within the suture mesenchyme; however, both the En1−/− mouse model and the Twist1+/− mouse model of Saethre-Chotzen syndrome demonstrate extensive lineage mixing leading to coronal suture fusion." (PMID 32916911, 2020). "Genes associated with the other syndromes (e.g., Carpenter [RAB23 gene, MEGF8 gene], Apert [FGFR2 gene], Crouzon [FGFR2 gene], Pfeiffer [FGFR2 gene, FGFR1 gene], and Saethre-Chotzen syndromes [TWIST1 gene]) were analyzed by WES analysis and none of these mutations were found on the patients." (PMID 34348791, 2021).